FLT3 (fms related receptor tyrosine kinase 3)
Diseases named in the same sentence as FLT3 in open-access papers (continued):
Sharing a sentence is not in itself a finding about the gene and the disease.
amyloidosis (3 papers, 2016 to 2025). A disorder characterized by the localized or diffuse accumulation of amyloid protein in various anatomic sites. "RANTES and VEGF are neuroprotective, MCP-1 and Fractalkine are antiapoptotic, FLT-3 regulates microglial activation, while GM-CSF reverses cognitive impairment and amyloidosis." (PMID 40710133, 2025). "Given that Flt3-Cre is expressed via the Y chromosome, which precludes direct examination of the fate-mapping reporter system in females, we focused our analyses on evaluation of effects of splenectomy on amyloid pathogenesis in female mice." (PMID 35511433, 2022). "To determine the functional contribution of circulating monocytes to amyloid plaque pathogenesis, we performed splenectomy on male APP/PS1mTmG;Flt3-Cre mice." (PMID 35511433, 2022). "FLT-3 can regulate microglial activation and G-MCSF reverse cognitive impairment and amyloidosis." (PMID 27403169, 2016).
B-cell lymphoma (3 papers, 2023 to 2025). "Using genomic polymerase chain reaction (PCR), conserved FLT3 mutations between species have been demonstrated in both the canine GL-1 cell line and in clinical specimens of canine B-cell lymphoma." (PMID 40563676, 2025). "B-cell lymphoma is the most common hematopoietic malignancy in both dogs and humans and shares many biological, genetic, and molecular characteristics, including the Feline McDonough Sarcoma (FMS)-like tyrosine kinase 3 (FLT3) mutation." (PMID 40563676, 2025).
breast tumors (3 papers, 2020 to 2024). "The results showed that CCL5 and IDH2 were not significantly differentially methylated in BRCA, while CCR7, EZR, IL8, and IL2RG were hypermethylated in normal tissues, and FLT3, MAPK10, and MMP9 were hypermethylated in breast tumor tissues." (PMID 38438469, 2024).
chronic lymphocytic leukemia (3 papers, 2020 to 2025). "Ibrutinib is primarily approved for chronic lymphocytic leukemia (CLL) but is also shown to inhibit FLT3-ITD in AML cells." (PMID 41226551, 2025).
differentiated thyroid carcinoma (3 papers, 2021). Differentiated thyroid carcinoma (DTC), also known as papillary or follicular thyroid carcinoma, is a slow-growing malignancy usually presenting in adults as an asymptomatic thyroid mass. "For instance, the PKI sorafenib inhibits the kinases RAF, BRAF, FLT3, VEGFR 1–3, PDGFR, c-KIT and RET and significantly improves progression-free survival compared with placebo in patients with progressive radioactive iodine-refractory differentiated thyroid cancer." (PMID 34888523, 2021).
endothelial dysfunction (3 papers, 2019 to 2025). In vascular diseases, endothelial dysfunction is a systemic pathological state of the endothelium (the inner lining of blood vessels) and can be broadly defined as an imbalance between vasodilating and vasoconstricting substances produced by (or acting on) the endothelium. "Whether the FLT3 wt blasts intrinsically cause more endothelial damage, leading to a more ‘malignant’ form of leukostasis, or whether the FLT3 wt AML patients had more endothelial dysfunction due to other factors (infection, chemotherapy toxicity) cannot be fully deciphered." (PMID 38201486, 2023). "Activation of Flt-3 pathway is thought to provide radioprotection to hematopoietic progenitor cells and reactive oxygen species produced by xanthine oxidase following gamma radiation may contribute to endothelial dysfunction and increased vascular stiffness." (PMID 30742630, 2019).
esophageal squamous cell carcinoma (3 papers, 2021 to 2025). Esophageal squamous cell carcinoma (ESCC) is a type of esophageal carcinoma (EC) that can affect any part of the esophagus, but is usually located in the upper or middle third. "Therefore, FL - Flt-3 is a potential molecular target for enhancing radiosensitivity of esophageal squamous cell carcinoma." (PMID 34040525, 2021).
fibrosarcoma (3 papers, 2016 to 2021). A malignant mesenchymal fibroblastic neoplasm affecting the soft tissue and bone. "Sorafenib is a small molecule targeting VEGFR-2 and VEGFR-3, rapidly accelerated fibrosarcoma (Raf), rearranged during transfection (RET), tyrosine-protein kinase KIT, FMS-like tyrosine kinase 3 (FLT-3), and PDGFR-β, with limited anti-tumor activity in NSCLC when used as a single-agent." (PMID 36046069, 2020). "Additionally, first-generation inhibitors block other targets, such as PDGF receptors (PDGFR), KIT (cluster of differentiation 117: CD117), b-rapidly accelerated fibrosarcoma (RAF), and Fms-like tyrosine kinase 3 (FLT-3), which are not substantially inhibited by axitinib." (PMID 26983443, 2016).
ischemic heart disease (3 papers, 2018 to 2024). "Until then, close monitoring of patients with underlying ischemic heart disease undergoing Flt3- or multi-targeting TKI treatment may be warranted." (PMID 37945814, 2024). "Both VEGF-C and VEGF-D are secreted glycoproteins that exhibit structural homology but have differential receptor binding (Flk-1 and Flt-3, respectively) and regulatory mechanism is a vital mediator to angiogenesis in ischemic heart disease in type 2 DM." (PMID 34904074, 2021). "Of interest, STAT3 is required for Flt3-dependent formation of DCs from bone marrow derived cells, and plays an important role in production of IL-1β, IL-6, and TNFα in macrophages of humans with coronary artery disease." (PMID 29800237, 2018).
medullary thyroid cancer (3 papers, 2019 to 2022). "Cabozantinib (XL184), targeting VEGFR1/2, MET, RET, KIT and FLT3, has been assessed in several cell line models and has been approved by the FDA for the treatment of progressive medullary thyroid cancer." (PMID 31040922, 2019).
myocardial infarction (3 papers, 2024 to 2026). Gross necrosis of the myocardium, as a result of interruption of the blood supply to the area, as in coronary thrombosis. "ANXA3 and SOCS3, as novel biomarkers for acute myocardial infarction (AMI), demonstrates significantly superior diagnostic performance compared to traditional markers CD34 and FLT3, with area under the ROC curve (AUC) exceeding 0.7, highlighting their stronger clinical relevance." (PMID 40760666, 2025). "Flt3 is expressed in the heart and upregulated after myocardial infarction (MI) in mice." (PMID 37945814, 2024). "Flt3 is expressed in the heart and its activation is cytoprotective in myocardial infarction (MI) in mice." (PMID 37945814, 2024).
Obesity (3 papers, 2016 to 2024). Accumulation of substantial excess body fat. "CNTNAP2, GLI2, DPT (dermatopontin), AEBP1, ITIH5, CXCL11, GDNF (glial cell derived neurotrophic factor), MCHR1, FLT3, ELANE (elastase, neutrophil expressed), OSMR (oncostatin M receptor) and IL15RA are involved in development of obesity, but these genes might be key for progression of HF." (PMID 34218797, 2021).
pericardial effusion (3 papers, 2020 to 2023). Fluid collection within the pericardial sac, usually due to inflammation. "Cumulative dose of known cardiotoxic drugs should be reduced as soon as possible, such as for nilotinib, ponatinib, or FLT3 inhibitors, or a single daily dose should be used for certain drugs, such as dasatinib, in order to reduce the risk of pleural and pericardial effusion." (PMID 33322351, 2020).
/T-cell lymphoma (2 papers, 2016 to 2022). "It has indeed been shown that the miR-150 target gene repertoire can highly differ between different hematopoietic malignancies, e.g., MYB, FLT3, CBL and EGR2 in MLL-rearranged AML cells, and DKC1 and AKT2 in NK/T-cell lymphoma." (PMID 35205272, 2022). "MYB, FLT3, and EGR2 have been identified as critical target genes of miR-150 in MLL-rearranged AML, while AKT2 is a direct target of miR-150 in NK/T-cell lymphoma." (PMID 27917123, 2016).
allergic asthma (2 papers, 2011 to 2020). A asthma with a basis in a pathological type I hypersensitivity reaction. "In addition, we examined the phenotype and immune cell population, as well as detailed immune responses, associated with Flt3 deficiency in allergic asthma." (PMID 33327561, 2020). "In conclusion, we revealed that Flt3-independent CD11b+ DCs direct Th2 responses with the elevated OX40L and are the primary cause of allergic asthma." (PMID 33327561, 2020). "This study identified the DC populations that primarily cause the initiation and development of allergic lung inflammation using Fms-like tyrosine kinase 3 (Flt3) knockout (KO) mice with allergen-induced allergic asthma." (PMID 33327561, 2020). "Therefore, we investigated which DC populations (CD103+ DCs versus CD11b+ DCs) are crucial for the initiation and development of allergic asthma in Flt3 KO mice." (PMID 33327561, 2020). "In addition, bone marrow-derived dendritic cells (BMDCs) from Flt3 KO mice directed Th2 immune responses in vitro, and the adoptive transfer of these BMDCs exacerbated allergic asthma with more marked Th2 responses than that of BMDCs from wild-type (WT) mice." (PMID 33327561, 2020). "Thus, it is important to evaluate the phenotypic and immunologic effects of Flt3 KO on allergic asthma." (PMID 33327561, 2020). "We found that DCs—independent of the Flt3 signal—were the major factor in advancing allergic asthma by directing the type 2 immune responses, which was confirmed through in vitro and in vivo studies." (PMID 33327561, 2020).
Autoimmunity (2 papers, 2014 to 2022). The occurrence of an immune reaction against the organism's own cells or tissues. "Star 27 should enable a reduction in FLT3-associated inflammation and autoimmunity while allowing KIT and CSF1R to compensate with classical DC maintenance." (PMID 25531068, 2014). "A specific intron variation in FLT3 causes the production of a truncated protein, with decreased levels of FLT3 receptor and increased circulating FLT3 ligand, which could lead to autoimmunity." (PMID 35844538, 2022).
cardiac hypertrophy (2 papers, 2023 to 2024). "The most significantly affected signaling pathways were EIF-2, IL-2, integrin, NGF, VEGF, estrogen receptor, IL-7, FLT3, FGF, oxytocin, cardiac hypertrophy, role of NFAT in cardiac hypertrophy, and neutrophil extracellular trap pathways." (PMID 38047311, 2024).
Cerebral ischemia (2 papers, 2021 to 2023). Restriction of arterial blood supply to the brain associated with insufficient oxygenation to support the metabolic requirements of the tissue. "One study into this kinase showed that FLT3 expression increased in undifferentiated SH-SY5Y cell model of cerebral ischemia." (PMID 37380886, 2023).
childhood leukemia (2 papers, 2020 to 2025). An acute or chronic leukemia that occurs during childhood. "Quizartinib has completed investigation through a Phase I clinical trial in combination with salvage chemotherapy in r/r childhood leukemia, both harboring FLT3 wild-type and FLT3-ITD mutations, and demonstrated 4/17 CR and 10/17 stable disease (SD)." (PMID 32050659, 2020). "These unexpected results led us to investigate whether the blockade of EZH2 may lead to the activation of alternative oncogenic pathways, such as FLT3 and its downstream signaling, previously reported for childhood leukemia." (PMID 40722046, 2025).
CMV infections (2 papers, 2022). "In order to clarify the issue, we analyzed the prospective RCT to explore the incidence and mortality of EBV and CMV infections in patients with FLT3-ITD AML with and without sorafenib maintenance post-transplantation." (PMID 36050712, 2022).
CNS leukemia (2 papers, 2022). "One case of symptomatic CNS leukemia was observed in a 69-year-old female patient with FLT3-ITD+ AML who displayed symptoms of peripheral neuropathy, insomnia, chronic gastritis, chronic enteritis and constipation." (PMID 35523692, 2022). "The second case of symptomatic CNS leukemia was observed in a heavily pretreated 70-year-old male patient with FLT3-ITD+ AML secondary to MDS." (PMID 35523692, 2022). "Of the 7 children with CNS leukemia, 1 was JAK2+, 1 was FLT3+, and 1 was MUC16+." (PMID 35733807, 2022).
colorectal adenocarcinoma (2 papers, 2017 to 2022). The most common type of colorectal carcinoma. "Midostaurin inhibited colorectal adenocarcinoma cell growth associated with the formation of dsDNA and ssDNA; the up-regulation of mRNA expression of cGAS, STING, IRF3, and IFNAR1; the down-regulation of Trex-1, c-Kit, and Flt3 protein expression." (PMID 36230769, 2022). "Midostaurin suppressed Flt3 and Trex-1 activation, and FLT3L activated both of these proteins in three colorectal adenocarcinoma cells." (PMID 36230769, 2022). "The protein expressions of Trex-1, c-KIT, and Flt3, but not PKCα/β/γ and VEGFR1, were down-regulated in midostaurin-treated colorectal adenocarcinoma cells and macrophages." (PMID 36230769, 2022).
depression (2 papers, 2011 to 2022). "For example, the ubiquitous protein, UBC, was abnormally expressed in schizophrenia samples and interacted with the maker genes of schizophrenia (i.e. TSC2, SCNN1A and USP2), bipolar disorder (i.e. MUSK), and major depression (i.e. MUSK and FLT3)." (PMID 22373040, 2011).
diabetes (2 papers, 2022 to 2024). "The coefficients for each parameter were as follows: 0.4029 for abnormal NT-pro BNP, 0.1706 for history of diabetes, 0.6376 for NPM1, 0.0294 for FLT3, 0.0383 for Ras, 0.1220 for WT1, 0.5206 for JAK2, 0.0055 for WBC, 0.0942 for RBC, and − 0.0007 for EF." (PMID 38273254, 2024). "It was reported that Fms-like tyrosine kinase 3 (FLT3) mediates PI3K/AKT signaling and treating with FLT3 ligand could significantly prevent the progression to diabetes in diabetic NOD mice." (PMID 36352450, 2022).
esophageal cancer (2 papers, 2014 to 2021). A primary or metastatic malignant neoplasm involving the esophagus. "The last surviving patient under observation in the group of FLT3-TKD positive patients died of esophageal cancer." (PMID 24608088, 2014).
essential thrombocythemia (2 papers, 2015 to 2022). A chronic myeloproliferative neoplasm that involves primarily the megakaryocytic lineage. "Unlike mutant N-Ras-mediated Socs2 downregulation, several hematopoietic malignancies driven by other oncogenic mutations demonstrate upregulated SOCS2 expression, such as JAK2V617F-positive essential thrombocythemia (ET), BCR/ABL-positive CMLs and FLT3-ITD AMLs." (PMID 35352806, 2022).
Ewing sarcoma (2 papers, 2012 to 2023). A small round cell tumor that lacks morphologic, immunohistochemical, and electron microscopic evidence of neuroectodermal differentiation. "The levels of expression of Flt-3 and FL in 12 tumor cell lines from neuroectodermal tumor (NET), Ewing's sarcoma (ES), and peripheral neuroectodermal tumor (PNET) and in 38 biopsies were analyzed." (PMID 21876694, 2012).
hemophagocytic lymphohistiocytosis (2 papers, 2021 to 2025). "We report the first case with mutations in FLT3, NOTCH2, and KMT2A, and associated hemophagocytic lymphohistiocytosis." (PMID 34292677, 2021). "They identified MILR1 and FLT3 as pre-infusion biomarkers predictive of severe CRS and noted that CRS may be an IFNγ-driven process with a protein signature overlapping with hemophagocytic lymphohistiocytosis." (PMID 40004863, 2025).
liver inflammatory disease (2 papers, 2011 to 2021). "Enhanced FLT3-AKT signaling in CBL-/- CBL-B-/- cDC1s suggests that attenuation of FLT3-AKT signaling may normalize cDC1 homeostasis and cure liver inflammatory disease in CBL-/-CBL-B-/- mice." (PMID 34630435, 2021).
lung squamous cell carcinoma (2 papers, 2023 to 2024). "Mutations in FLT3 are rare in tumor samples from patients with squamous cell lung cancer and most reported mutations are of unknown significance." (PMID 36697489, 2023). "We show that pacritinib blocks glucose consumption in squamous cell lung cancer cells by inhibiting FLT3." (PMID 36697489, 2023). "Our study identifies FLT3 inhibitors as a new class of inhibitors that can block glucose consumption in squamous cell lung cancer." (PMID 36697489, 2023). "In conclusion, we identify pacritinib as a strong inhibitor of squamous cell lung cancer glucose consumption that functions by inhibiting FLT3 and limiting Hexokinase 1 expression." (PMID 36697489, 2023). "Additional FLT3 inhibitors blocked glucose consumption in squamous cell lung cancer cells." (PMID 36697489, 2023). "However, the fact that we show that pacritinib blocks glucose consumption in squamous cell lung cancer in vivo without affecting glucose consumption in healthy tissues suggests that a role for FLT3 in driving glucose consumption is cancer specific." (PMID 36697489, 2023). "A role for FLT3 in squamous cell lung cancer is not well-studied." (PMID 36697489, 2023). "Overexpression of FLT3 but not JAK2 significantly increased glucose consumption and blocked the ability of pacritinib to inhibit glucose consumption in squamous cell lung cancer cells." (PMID 36697489, 2023).
mast cell tumor (2 papers, 2022 to 2023). "This study is the first to report that FLT3 mutations occur in canine mast cell tumors using PCR analysis of genomic DNA and a hot-spot sequencing approach on a cohort of 20 MCT cases." (PMID 36072760, 2022). "Toceranib (Palladia), the first FDA-approved first tyrosine kinase inhibitor for treating dogs with mast cell tumor, targets KIT, VEGFR, FLT3 and PDGFR." (PMID 38201229, 2023).
mucositis (2 papers, 2020 to 2021). Mucositis is inflammation and damage of the mucous membranes lining the mouth and other parts of the gastrointestinal (GI) tract. "Another patient with FLT3 positive disease who experienced grade 2 mucositis was concomitantly treated with the radiosensitizer sorafenib." (PMID 34046361, 2021).
osteoporosis (2 papers, 2024 to 2025). A condition of reduced bone mass, with decreased cortical thickness and a decrease in the number and size of the trabeculae of cancellous bone (but normal chemical composition), resulting in increased fracture incidence. "In this study, we identified five key genes related to the circadian rhythm in osteoporosis (RAB5C, ECE1, FLT3, FCGR2A, and APPL1) using bioinformatics and machine learning approaches." (PMID 40642528, 2025). "In this study, the random forest model was used to screen out five key ferroptosis genes, including CP, HAMP, HMOX1, FLT3, and SLC2A3, and these 5 differentially expressed key ferroptosis genes were preliminarily verified in the osteoporosis model constructed." (PMID 38650009, 2024).
psoriasis (2 papers, 2017 to 2025). An autoimmune condition characterized by red, well-delineated plaques with silvery scales that are usually on the extensor surfaces and scalp. "Targeted inhibition of FLT3 almost completely cured the psoriasis-like disease." (PMID 28364278, 2017). "Interestingly, a significant accumulation of FLT3+CD11c+ DCs in human psoriatic lesions and in the skin of experimental preclinical K14-VEGF transgenic homozygous mice, a mouse model for psoriasis." (PMID 28364278, 2017). "Similarly, NOX4, CDK5, FLT3, ER‐α, and CDK1 are targets for psoriasis treatment." (PMID 41323822, 2025).
rectal adenocarcinoma (2 papers, 2023 to 2024). "The efficacy of sorafenib in targeting FLT3 amplification has been demonstrated in various studies, including a clinical case study involving a rectal adenocarcinoma patient with multiple genetic alterations, including FLT3 amplification." (PMID 39011472, 2024). "Most commonly gained or lost genes seen in rectal adenocarcinoma (FLT3, CDX2, GNAS, BCL2, SMAD4, MALT1) are not found in rectal squamous cell carcinoma." (PMID 36357817, 2023).
refractory anemia (2 papers, 2014 to 2016). "Among 32 AMLDNMT3A/FLT3/NPM1 cases with FAB classification data, 10 (31%) were M4; 8 (25%) were M5; 6 (19%) were M1; 6 (19%) were M2; 1 (3%) was M0; and, 1 (3%) was refractory anemia with excess blasts in transformation." (PMID 25281355, 2014).